RB1 (RB transcriptional corepressor 1)
Diseases named in the same sentence as RB1 in open-access papers (continued):
Sharing a sentence is not in itself a finding about the gene and the disease.
tumor (continued). "This example of a context where RB-E2F transcriptional control may play a tumor suppressive role is particularly relevant because pituitary tumorigenesis in Rb1+/- mice is dependent on Sox2." (PMID 30703085, 2019). "Silencing of Cdkn2b is indispensable for Rb1 phosphorylation and tumor induction." (PMID 30910991, 2019). "Inactivation of the RB1 gene is thought to be the main reason for the development of the tumor." (PMID 31798638, 2019). "Some tumours with wild type RB1 have shown to exhibit chromothripsis, where alternative mechanisms of RB1 deregulation, such as overexpression/amplification of cyclin D1 (CCD1) and/or inactivation of cyclin dependent kinase inhibitor 2A (CDKN2A), have been identified." (PMID 31619019, 2019). "The five TLR proteins were identified in tumor cells, in both GBM cell lineages with mutational status consistent for the mesenchymal subtype (U87MG and A172): RB transcriptional corepressor (RB1) missense mutation in A172, and neurofibromin (NF1) missense and deletion mutation in U87MG." (PMID 29912993, 2018). "All known β-HPV E7 proteins contain canonical LXCXE (L, leucine; C, cysteine; E, glutamate; X, any amino acid)-based binding sites for the retinoblastoma tumor suppressor family of proteins and many have been documented to bind RB1, RBL1 (p107), and RBL2 (p130)." (PMID 29568286, 2018). "RB1 might also function as a tumor suppressor by promoting differentiation of lineage-committed cells and survival of postmitotic neurons, and preventing cellular reprogramming." (PMID 29914980, 2018). "Transcript expression of SKP2, a SCFSKP component, was elevated in RB1-defective TNBCs, suggesting that in these tumours, SKP2 activity might buffer the effects of RB1 dysfunction." (PMID 29915391, 2018). "Thus, the study of the Sanger cell line dataset supports the correlation between vinorelbine sensitivity and low FBXW7 or RB1 expression in tumor cell lines derived from specific tissues." (PMID 29689640, 2018). "Combined with the histone-GFP reporter live imaging assay we developed, our somatic screen provides a rapid method to test chromatin remodelers and further dissect the mechanism controlling RB1-dependent proliferation and survival in neurogenesis and tumor suppression." (PMID 29914980, 2018). "The analysis of chemoresistant patients showed that the acquired resistance to chemotherapy was associated with inactivating gene breakages at the level of the tumor suppressors RB1, NF1, RAD51B and PTEN and resistant/refractory tumors are frequently associated with CCNE1 amplifications." (PMID 29389895, 2018). "Tumor cells lacking RB1 had increased susceptibility to BETi-mediated tumor cell death, with cells surviving BET inhibition displaying pharmacodynamic inhibition of BET family member function." (PMID 30400835, 2018). "Interestingly, loss of RB1 has been associated with a poor response to hormone therapy, and expression of LCP1 has been proposed as a biomarker of advanced tumour stage and tumour severity." (PMID 29665859, 2018). "Similarly, the poor prognosis group of 5-gene score showed shorter DSS (p = 0.045) and early RFS (p = 0.023) as well as a significant association with microvascular invasion, tumor size (> 5 cm), elevated AFP levels, and RB1 mutations." (PMID 29776391, 2018).
tumor (continued). "RB1 deletion (M7) or LOH (M9) were detected in all tumor regions." (PMID 29050228, 2017). "RB1, a classic tumor suppressor, is frequently inactivated in many malignances." (PMID 27283490, 2017). "Rb1 mutations in mice did not result in tumor formation and it seem as the family member p107 takes the role of Rb1 in the murine retina." (PMID 29124525, 2017). "In this study, we provide evidences that suggest a plausible mechanism linking AHR and HCC via targeting of HDAC8, which promotes tumor cell growth and may restrain the expression of RB1 tumor suppressors in HCCs." (PMID 27283490, 2017). "Rb1 is a vital tumor suppressor that is often lost in advanced CaP." (PMID 28978058, 2017). "We were able to identify, however, truncating mutations in RB1 and MED12 that are very likely to be somatic oncogenic drivers in this patient given the well-established role of these two genes as tumor suppressors across multiple tumor types." (PMID 28390395, 2017). "The first tumor had a deletion of 13q14 that included the RB1 and FOXO1 loci." (PMID 28193293, 2017). "Conversely, American ginseng had a low Rg1:Rb1 ratio and Rb1 was shown to inhibit tumor growth." (PMID 28471389, 2017). "We also found that decreased level of tumor-suppressor RB1 in tumor tissues." (PMID 28300839, 2017). "At the same time the tumor suppressor gene Rb1 has been shown to have decreased expression and may also play a role in tumor progression." (PMID 28819469, 2017). "Interestingly, an inverse correlation was found in tumor tissues between Linc00441 and RB1 expression (P<0.001 and R2=0.45)." (PMID 28300839, 2017). "Methylation of the RB1 promoter is known to be the causative ‘first hit’ in about 8% of unilateral non-heritable tumours and about 88% of those were reported to have RB1 gross deletions or loss of heterozygosity as ‘second hit’." (PMID 28575107, 2017). "Immunohistochemical staining of tumor sections with antibodies against pRb and phosphorylated Rb (ppRb) displayed high levels of pRb and ppRb in both RB1+/+ and RB1+/− tumors with MYCN amplification compared to no expression of these proteins in a classic RB1−/−, MYCN‐low tumor." (PMID 28211617, 2017). "Tumor induction was significantly accelerated by rb1-TALENs in the tp53e7/e7 mutant background." (PMID 28903419, 2017). "In addition to RB1 as the rate-limiting step for tumor initiation, there are multiple genes (oncogenes and tumor suppressor genes) that undergo mutations, such as MYCN gain, loss of 16q, etc., thereby promoting tumorigenesis." (PMID 29162051, 2017). "By this method, almost universal rb1 and rbl1 INDELs (88% to 100%) could be demonstrated within the neoplasms." (PMID 27739525, 2016).
tumor (continued). "At first glance, such changes might seem unimportant, particularly when compared with the abrupt cell cycle arrest seen when pRB is expressed in RB1 mutant tumor cell lines such as Saos2 cells that are primed for arrest and senescence when they regain pRB." (PMID 27401552, 2016). "More broadly, an E2F-independent paradigm of tumor suppression is being developed for RB1." (PMID 26925970, 2016). "High-level focal amplification of MYCN and RB1 mutations by was not considered significantly inversely correlated because tumor T21 acquired both alterations (single nucleotide frameshift deletion in exon 15 of RB1; NM_000321:c.1397delA:p.E466fs)." (PMID 27126562, 2016). "Activated transcription of RB1, together with p21 and p16, was shown to suppress tumor cell growth." (PMID 27226982, 2016). "There are no mutational studies of RB1, for example, showing that the precise elimination of pRB's interaction with a single partner (or even a class of proteins) eliminates its tumor suppressor activity." (PMID 27401552, 2016). "Importantly, our findings in the current study suggest that in the natural tumor host cells MCPyV inactivation of RB1 appears to be the predominant and in some MCC cell lines the only essential function of MCPyV-LT to support growth of these cells." (PMID 27121059, 2016). "Immunohistochemistry on tissue sections revealed that in the metastasis all tumor cells were negative for RB1, in line with loss of both alleles of the RB1 gene." (PMID 27121059, 2016). "Thus, our results suggest that RB1 is the dominant tumor suppressor PP in MCC, and that inactivation of RB1 by MCPyV-LT is largely sufficient for its growth supporting function in established MCPyV-positive MCC cells." (PMID 27121059, 2016). "Several strategies have been described for targeting RB1 mutant tumor cells." (PMID 27401552, 2016). "We proposed that miR-132/-212 targets RB1 and promotes tumor proliferation." (PMID 26735889, 2016). "For instance, downregulation of miR-106a may inhibit cell proliferation by activation of RB1 tumor suppressor." (PMID 27226982, 2016). "Furthermore, RB1-mutated tumors showed significantly smaller T2-FLAIR hyperintensity (26,354.4 mm3 average difference, p = 0.015) and total tumor volume (34,467.2 mm3 average difference, p = 0.020)." (PMID 26337765, 2015). "The genes CDKN2A, CDKN2B, and RB1 function as tumor suppressors; their decreased expression occurs via several mechanisms, including methylation, and contributes to the development of neoplasias." (PMID 26317630, 2015). "Several clinical studies suggest, indeed, that RB1 might represent a predictive marker of response to therapy for various tumor types." (PMID 26160835, 2015). "Its overexpression may facilitate the malignant transformation of the lymphoid cell and tumor progression, resulting in the deregulation of cell cycle control by inhibiting the suppressor effect of retinoblastoma 1 (RB1) and the cell cycle inhibitor p27." (PMID 25888530, 2015). "RB1 ability to prevent apoptosis might seem inconsistent with its oncosuppressive role, since apoptosis inhibition is more likely to favor tumor growth." (PMID 26160835, 2015). "A deletion in the classical tumour suppressor gene, RB1, was observed in one (BR5) of our 13 cases." (PMID 26205622, 2015). "DNA from patient blood and/or tumor was used for RB1 gene targeted sequencing." (PMID 25928201, 2015). "RB1 is highly regulated and critical for cell cycle progression and tumor suppression." (PMID 26265441, 2015). "Indeed, the canonical model for the tumor suppressive action of RB1, which emerged from these early studies, is based on its ability to inhibit the G1-S transition through the repression of E2F target genes involved in DNA synthesis and cell cycle progression." (PMID 26160835, 2015).
tumor (continued). "RB1 mutations could be predicted by T2-FLAIR hyperintensity (AUC = 0.66, p = 0.022) and total tumor volume (AUC = 0.68, p = 0.011)." (PMID 26337765, 2015). "Therefore, therole of Rb1 in tumor suppression is likely less important from anevolutionary standpoint than its ancient broad functions in regulating cellulardifferentiation and tissue formation." (PMID 26575287, 2015). "Given the central role of RB1 in regulating cellular processes that are crucial for both defense against tumor progression and response to cancer treatments, a careful analysis of RB1 status could be critical to guide therapeutic decisions." (PMID 26160835, 2015). "On the other hand, tumors with one or without RB1 mutation were characterized by a late age at diagnosis (median 35 months) and an advanced stage of tumor." (PMID 25602518, 2015). "Given that RB1 loss caused embryonic lethality, we hypothesized that HPV oncogenes may also cause lethality and inhibit tumor growth via an E7-RB1-E2F pathway." (PMID 26670255, 2015). "Indeed, several studies on patients with different cancer types suggest that RB1 status affects tumor sensitivity to treatments and clinical outcome." (PMID 26160835, 2015). "Moreover, the development of more rigorous, standardized methods to assess RB1 status in tumor specimens is required before RB1 can be used as a predictive marker to guide therapeutic decisions in clinical practice." (PMID 26160835, 2015). "Inactivation of the retinoblastoma (RB1) tumor suppressor occurs with such a high frequency in cancer — either directly, through mutations, or indirectly, through the altered expression of RB1 regulators — to be proposed as a fundamental event for tumor development." (PMID 26160835, 2015). "Based on our previous study showing that miR-155 is a downstream mediator of the function of MCRS1 in cellular proliferation and the EMT process, we examined whether MCRS1 regulated tumor cell growth through miR-155 targeting of the Rb1 gene." (PMID 26467212, 2015). "MCRS1 is a candidate oncogene, and Rb1 is one of the most important tumor suppression genes." (PMID 26467212, 2015). "The fading RB1 expression in MLS/RCLS may thus result from a normal downregulation in connection with growth cessation of many tumor cells." (PMID 25093008, 2014). "RB1 for example is commonly mutated in OS but miRNA-mediated silencing of the gene might be an alternative mechanism to inactivate the tumor suppressor properties of RB1." (PMID 24955218, 2014). "As demonstrated by the current study, when administered at the same dose, Rg1 treatment achieved a greater effect on inhibiting tumor growth compared to that from the Rb1 treatment, while similar effect of cardioprotection was observed from both Rg1 and Rb1 treatment." (PMID 24903055, 2014). "Taken together, the current study demonstrated for the first time that PNS and its major activity components Rg1, Rb1 and R1 effectively suppressed tumor growth and attenuated myocardial ischemic injuries in the complex mouse model featuring simultaneous presentation of both disease conditions." (PMID 24903055, 2014). "Three chromosomal regions were of interest, including a deletion of 5q12–21 found in 26% of tumors, a deletion of 13q14–21 also found in 26% of tumors that contains the RB1 tumor suppressor, and amplification at 1p34 present in 39%, which contains the L-Myc (MYCL1) oncogene." (PMID 25329450, 2014). "It has been shown that PNS, Rg1, Rb1 or R1 display antiproliferative activities in tumor cells." (PMID 24903055, 2014).
tumor (continued). "Moreover, it is notable that PNS exhibited the most significant effects on tumor inhibition and cardioprotection when given at a dose that contained comparable amounts of the Rg1, Rb1 and R1." (PMID 24903055, 2014). "The SJRB011 retinoblastoma had abundant nuclear RB1 protein in virtually all the tumor cells." (PMID 24509483, 2014). "We compared expression of Pax3:Foxo1a expressing primary tumor cell cultures with or without Rb1 loss (n = 3 biological replicates each) to proliferating or differentiating C2C12 myoblasts as a control for the aRMS cell of origin." (PMID 24274149, 2013). "Indeed, when we plotted drug sensitivity ranked by RB1 status and superimposed the curves, we found that RB+ tumors were more sensitive than RB− tumor cells to any of the FDA approved drugs." (PMID 24265703, 2013). "Finally, we proposed a hypothetical model to explain the role of the miR-17 family in regulating cell cycle and tumor progression by targeting the RB1 protein in NSCLC." (PMID 24200043, 2013). "Also, changes in tumour suppressor gene-related regions, such as 9p21.3 (CDKN2A) 9p23-24.1 (PTPRD), 13q14.2 (RB1), were significantly fewer in tumours with ALK fusion." (PMID 23289484, 2013). "Rb1 immunostaining appeared as strong homogenous nuclear staining in >50% of tumor cells." (PMID 23809295, 2013). "Some of the miRNAs with recently identified targets in vitro in various tumor settings other than GIST include: miR-132 targeting Rb1, miR-193b targeting CCND1 and Mcl-1, miR-455-3p targeting Smad2, miR-125b targeting Mcl-1 and Bcl-2 and miR-542-5p targeting survivin." (PMID 23717541, 2013). "The Rb1 gene was the first bona fide tumor suppressor identified and cloned more than 25 years ago." (PMID 24381932, 2013). "However, the CN loss of chromosome 13 is intriguing because this affects the loci of well-characterized tumor suppressor genes such as RB1 and BRCA2." (PMID 23577124, 2013). "Several lines of evidence suggest that the tumor suppressor function of 13q14.3 distal to RB1 is multigenic and is not inactivated by mutation, but rather by transcriptional deregulation." (PMID 23593011, 2013). "Retinoblastoma 1 (Rb1) was the first identified tumor suppressor." (PMID 23802096, 2013). "A number of other relatively small intra-genic aberrations were also detected, including a focal deletion in PTEN in a basal-like tumor, an intra-genic deletion in RB1 in a different basal-like tumor, and a small RB1 amplification in yet a third basal-like tumor." (PMID 23284754, 2012). "A limitation of our analysis is that we did not screen the tumor DNA for gene mutations or ascertain gene expression levels; nevertheless, we found that RB1 and RBAK are differentially methylated between the papillary serous and normal fallopian tube samples." (PMID 22403726, 2012). "Surprisingly, Rb 116 tumor cells displayed an atypical perinuclear immunoreactivity to RB1." (PMID 23233783, 2012). "Loss of heterozygosity in RB1 has been reported in uterine LMS, which may confer an increased susceptibility to this tumor in this population." (PMID 23036192, 2012).